NFKB1 (nuclear factor kappa B subunit 1)
Diseases named in the same sentence as NFKB1 in open-access papers (continued):
Sharing a sentence is not in itself a finding about the gene and the disease.
infection (2,774 papers, 2003 to 2026). The state of being infected such as from the introduction of a foreign agent such as serum, vaccine, antigenic substance or organism. "Taken together with our cellular findings, it would appear that in the absence of haploinsufficiency, variation and regulation of expression is more important than overall NFKB1 activity in altering risk of infection or inflammatory disease." (PMID 38232728, 2024). "We identified an insertion-deletion variant thought to affect NFKB1 expression as a causal variant—central to serological responses to diverse infectious agents, risk of infection, immune cell survival, antibody production, and inflammation." (PMID 38232728, 2024). "Because of the susceptibility of Nfkb1−/− mice to infection when housed under normal conditions, animals were followed in a pathogen-free environment and sacrificed when they displayed signs associated with a terminal state." (PMID 25553648, 2014). "In contrast NF-κB2 p100 was fully processed to p52 in the gastric corpus of Nfkb1−/− mice following infection, this was also associated with a significant increase in DNA binding of this sub-unit in infected Nfkb1−/− mice compared with infected WT mice." (PMID 23975431, 2013). "Our study showed that genetic polymorphism of the NFκB1 gene may influence how patients responded to H1N1pdm09 infection." (PMID 36296162, 2022). "On the other hand, infection with MOK023 caused a more sustained NFKB1 induction." (PMID 34740333, 2021). "Previous researches demonstrated that Nfkb1, along with other pathway components such as Nfkbia, Rel, and Relb, forms dynamic complexes to modulate gene expression in response to infection stimuli." (PMID 40248690, 2025). "RT-qPCR analysis confirmed the significant upregulation of Tnf, Malt1, Nfkb1, and Nfkb2 following infection, consistent with transcriptomic findings." (PMID 40248690, 2025). "NFKB1, also known as nuclear factor kappa-light-chain-enhancer of activated B cells, is crucial in regulating the immune response to infection." (PMID 41024254, 2025). "The modulation of terms related to pain and inflammation linked to interleukin-1, and strictly related to the over-expression of NFKB1, was also observed as a possible by-product of the ongoing infection." (PMID 40890612, 2025). "Transcriptomic profiling of immune response to pathogens suggests that NFKB1 forms part of a larger set of genes involved in regulation of immune response to a wide range of pathogen infections." (PMID 38232728, 2024). "NFκB1 and NFκB2 upregulated after 3 h of F. nucleatum-infection, and the inflammatory-related genes in the NF-κB signaling pathway were serially elevated with time." (PMID 36754953, 2023). "During the course of infection, Salmonella initiates epithelial inflammation and the rapid induction of pro-inflammatory cytokines via calcium-mediated activation of NFKB1." (PMID 37009487, 2023). "Here, we found that both colonic and ileal networks generated with CARNIVAL shared similar transcription factors, including ATF2/3, FOS, JUN, STAT1, and NFKB1, which were all upregulated in both tissues upon infection." (PMID 35501398, 2022). "Significant differences (p < 0.05) in the expression of only STAT1, STAT4, TRAF6, and NFKB1 factors were observed for the different types of macrophages, at different times of infection." (PMID 35774406, 2022). "Most noticeably, Nsp1-K164A/H165A infection had least effects on the expressions of proinflammatory markers, such as Mx2, Ifit3, Tlr6, Cxcl10, and Nfkb1." (PMID 36357440, 2022). "A recent study demonstrated that IFN-γ and tumor necrosis factor-alpha (TNF-α) levels increased steadily in infected D2.129P2 (B6)-Nfκb1 wild-type mice, peaking at day 10 post-infection (p.i.)and declining to uninfected levels by day 20 p.i.." (PMID 35740465, 2022).
infection (continued). "This is consistent with the known Nfkb1-/- mouse phenotypes such as defective responses to infection and specific antibody production." (PMID 34573120, 2021). "Whereas the signaling pathways enriched in subtype S2 primarily regulated the MAPK signaling pathway and osteoclast differentiation, as well as the infection of virus and E. coli bacteria, targeting the down-regulated TFs, such as NFKB1, FOS, and JUN." (PMID 33777111, 2021). "Siva1–205 and Nfkb1–210 lncRNAs were of higher abundance during RH infection of wild type and Myd88 KO macrophages." (PMID 33622246, 2021). "We found that Types I,II,III tachyzoites infection of cells all affected nuclear localization of NFκB1 and STAT3." (PMID 28904337, 2017). "Compared with the OVA-specific memory CD8+ T cells from Wt donors, we observed that memory T cells from Cd28−/− or Ox40−/− donors had significantly reduced upregulation in the mRNA expression of c-Myc and Nfkb1 at day 35 post-infection of VV-OVA." (PMID 26791245, 2016). "As the infection progressed, caspases 3, 8 and 9 were downregulated compared to the uninfected cultures at 72 hours, surprisingly together with NFκB1, but the Bcl-2 levels were increased." (PMID 25005804, 2014). "The products of the IKBKE and NFKB1 genes are central to the NF-κB signaling pathway that regulates the expression of many immune-related genes following infection." (PMID 25324841, 2014). "Consistent with previous results, LPS also induced higher levels of Il12b in Nfkb1−/− cells than in control cells following infection with vector alone." (PMID 22427889, 2012). "Genes linked to STAT3 during infection were associated with GO terms such as regulation of cell proliferation (CCND1, JUNB), negative regulation of apoptosis (MCL-1, NFKB1), cytokine-mediated signaling pathway (IL10RA, SOCS1), and immune system process (CRK, IRF9)." (PMID 41115066, 2025). "Notably, our study observed morphological changes in macrophages post-infection, along with upregulation of key NF-κB pathway genes (Nfkb1, Nfkb2, Tnf, and Malt1), further establishing F. nucleatum’s contribution to an immunosuppressive TME in CRC." (PMID 40248690, 2025). "Despite moderate increases in the relative number of circulating lymphocytes, reduced NFKB1 expression in T cells may result in impaired T cell function, thereby making them less responsive to infection." (PMID 38232728, 2024). "Thus, it is conceivable that in NFKB1 variant carriers, the combined excessive activation of the NLRP3 inflammasome and IFN-I pathways triggered by trauma or minor infection predispose patients to life-threatening inflammatory responses and tissue necrosis." (PMID 38593810, 2024). "Differently, although shE6 and shE7 vectors infection could decrease Rel and Nfκb1 expression of SiHa cells(these two P values are less than 0.05), E6OE and E7OE vector could not correspondingly increase the Rel and Nfκb1 expression in C33-A cells." (PMID 36457028, 2022). "In this study, we analyzed the NFκB1 gene of 36 Caucasian patients admitted in the intensive care unit (ICU) in several hospitals in Canada and evaluated the associations of the NFκB1 gene SNPs with the risk of severe response to H1N1pdm09 infection." (PMID 36296162, 2022). "Indeed, aligned with prior reports that O. tsutsugamushi stimulates the NF-κB response initially following invasion but then actively represses it as infection proceeds, NFKB1 and NFKB2 were among several genes upregulated at 4 h but downregulated at 48 h." (PMID 34340535, 2021). "Infection by genetically diverse clinical strains of M. tuberculosis revealed an upregulation of NFKB1 and NFKB2 transcriptional factors that lead to the transcription of IL1β, while IL18 was slightly down-regulated at 48 h infection by East-Asian and Euro-American lineages." (PMID 34502407, 2021).
infection (continued). "Three of those genes, IL1A (interleukin 1 alpha), EDN1 (endothelin 1) and NFKB1 (nuclear factor of kappa light polypeptide gene enhancer in B-cells 1) were also found to be activated in pharyngeal and lung epithelial cell cultures in response to infection with Moraxella catarrhalis." (PMID 26125632, 2015). "For instance, L. amazonensis interferes with NF-κB TF function through downregulation of RELA, NFKB1, and NFKB2 during early infection in BMDM." (PMID 39639867, 2024). "Our findings highlighted distinct differences between the infection groups of CT-P10 and CT-P120 PEDV strains, specifically in the expression levels of proteins such as TRAF3, IRF3, NFKB1, and ISG15." (PMID 37515115, 2023). "Simultaneously, the combined effects of infection at MOI of 0.0001 and irradiation resulted in upregulation in NFκB1 (P = 0.05)." (PMID 25005804, 2014). "The real time qRT-PCR verification performed for the NFKB1 and the TBK1 genes, both of which are represented in the infection signature panel, supports the reliability of this method for the detection of a gene infection signature for BTB." (PMID 17974019, 2007). "When Nfkb1–/– mice were inoculated with RML6 they showed first signs of disease by day 143 p.i. and the end stage of disease at 153 ± 5.6 days after infection." (PMID 17573907, 2007). "Notably, myeloid cells in AG ferrets showed significantly elevated expression of inflammatory cytokines, including IL-1β, IL-10, IL-18, NFκB1, and S100A8, as well as upregulated IFNGR2 expression throughout infection, especially 4dpi." (PMID 40794649, 2025). "Compared with infection with the WT strain, infection with the LLM deletion strain significantly reduced the mRNA expression of nuclear factor kappa B subunit 1 (NFKB1) (3.37-fold, p < 0.001) and AP1 or JUN (3.42-fold, p < 0.001) in the NF-κB and MAPK/AP-1pro-inflammatory signaling pathways." (PMID 40076391, 2025). "Even with past infection of H. pylori, it still may trigger CXCR2 signaling to induce cellular senescence through upregulating the related cytokines like NFKB1." (PMID 40051725, 2025). "Surprisingly, the two subunits of NFKB – NFkB1 and NFkB 2 were not differentially expressed in spheroids undergoing Neisseria (Log2FC 0.61, -0.26) and Borrelia (Log2FC -0.030, 0.44) infection." (PMID 38179419, 2023). "Notably, NFKB1 and NFKB2, two central activators of genes involved in inflammation and immune function, were significantly upregulated at 3 h after F. nucleatum-infection and showed sustained activation at 6 h and 12 h." (PMID 36754953, 2023). "Conversely, irrespective of infection, JQ-1 suppressed NFκB-1 TF activity and induced NFκB-2 TF activity." (PMID 37747932, 2023). "Thus, infection with H. pylori wt bacteria triggers a quick response of the host that results in activation of transcription factor genes JUN and NFKB1." (PMID 37193047, 2022). "No increase in NFκB1 mRNA levels in infected cells compared to uninfected controls was observed at any time point of infection." (PMID 33857149, 2021). "Moreover, several TFs, such as NFKB1, p65, JUN, SP1 and STAT3, were demonstrated previously to be involved in the regulation of lung inflammation and immunity during pathogen infection or external stimulation." (PMID 32592597, 2020). "Comparison of the transcriptional profiles between the dietary groups revealed that expression of nfkb-1 was not significantly influenced by diet or by infection in either the lungs or the blood." (PMID 31437249, 2019). "Previous studies have successfully identified ASB from ChIP-seq for all NF-κB subunits in LCLs and NFKB1 footprints are induced in response to infection." (PMID 30254052, 2018). "Likewise, host immune-related genes, such as VCAM1, NFKB1 and TLR2/3, were also elevated at the early stage in the infection group, which were consistent with many previous reports." (PMID 28486945, 2017).
infection (continued). "Lastly, we confirmed by in vitro assays that knocking down NFKB1 (via infection with a turboRFP shRNA-containing vector rather than an empty control vector) increases phagocytosis of MCF7 cells by macrophages." (PMID 28378740, 2017). "Nfkb1, lrf3, and Irf5 gene expression was barely influenced by TMEV infection." (PMID 26703877, 2015). "This may be because the bacteria can induce cellular senescence even in the absence of an active infection by upregulation of cytokines, such as tumor necrosis factor-alpha and interleukin-1 beta, which may induce through NFKB1 to activate CXCR2 signaling." (PMID 40051725, 2025). "The NFκB complex consists of 5 proteins [NFκB1 (p105), NFκB2 (p100), RELA (p65), RELB and REL (c-Rel)] and, upon activation, provides a powerful defense mechanism against infection and stress; regulation of the complex in managed in part by families of NFκB inhibitor genes (IκB) and kinases (IKK)." (PMID 27078000, 2016). "Notably, at the 24-h time point, both IKBKE and NFKB1 were up-regulated in the M. bovis-infected MDM relative to BCG-infected MDM, suggesting that there is increased activation of NF-κB signaling following infection with the virulent mycobacterial strain." (PMID 25324841, 2014). "Interestingly, before infection, the expression levels of many of these master regulators (e.g., REL, NFKB1, RELB, IRF2, IRF9) were different across the three species, while post-infection, their expression converged to practically the same level, regardless of species." (PMID 21187902, 2010).
bacterial infection (342 papers, 2004 to 2026). "Similar to NFKB1 loss of function variants in humans, Nfkb1-/- mice are more susceptible to bacterial infection and have significantly reduced peripheral B cell numbers." (PMID 34721373, 2021). "The up-regulation of NFKB1 with all challenges was consistent with previous studies where bacterial infections up-regulated NFKB1 transcription in bovine mammary cells, confirming the ability of the mammary gland to mount a robust innate immune response." (PMID 28396748, 2017). "While clearance of bacterial infections is not altered by the absence of NFκB1, NFκB p50 deficient mice exhibit excessive and prolonged inflammation following bacterial clearance, and the consequence of inflammatory injuries is more severe in the absence of NFκB p50." (PMID 22761754, 2012).
neurodegenerative disease (264 papers, 2008 to 2026). A disorder of the central nervous system characterized by gradual and progressive loss of neural tissue and neurologic function. "Previous studies have highlighted the roles of NFKB1 and PTEN in regulating neuroinflammation and apoptosis, which are involved in neurodegenerative diseases." (PMID 41427016, 2025).
cardiovascular diseases (235 papers, 2006 to 2026). "In the present study, we also clearly demonstrated that the patients at high risk of cardiovascular diseases with NFKB1 gene DD mutant genotype have a significantly higher risk of MACCEs than those without mutant genotypes." (PMID 35831800, 2022). "The NFKB1-94ins/del ATTG polymorphism has been extensively studied in cardiovascular diseases." (PMID 26075620, 2015). "Therefore, it is necessary to identify NFKB1 genotypes in the population at high risk of cardiovascular diseases, and for those with DD genotype aggressive clinical pharmacological and healthy lifestyle interventions should be implemented to reduce the occurrence of MACCEs." (PMID 35831800, 2022). "Therefore, identifying NFKB1 gene rs28362491 mutant may be used as a good way for guiding the standardized management of patients with high-risk of cardiovascular diseases." (PMID 35831800, 2022). "These evidences suggest that NFKB1 gene mutant DD genotype may be a functional mutant in cardiovascular diseases." (PMID 30910844, 2019). "Thus, DSSM exerts effects against cardiovascular diseases by targeting JUN, TNF, NFKB1, FOS, and BCL2." (PMID 29348768, 2017). "In this study, pathway enrichment analysis showing the presence of NFKB1 and BCL2 in module 1 indicated a particular association with the NF-κB signalling pathway, indicating that NFKB1 and BCL2 may be correlated with the effects of DSSM against cardiovascular diseases through this pathway." (PMID 29348768, 2017).
kidney disease (204 papers, 2008 to 2026). "NFKB1 is involved in regulating the expression of a variety of genes involved in inflammation, cell proliferation, and survival; its activation is a critical issue in the inflammatory response, and its dysregulation is associated with various diseases, including liver and kidney diseases." (PMID 40238193, 2025).
kidney (118 papers, 2007 to 2026). "We have showed that the variant del genotype of the NFKB1 -94 ins/del ATTG polymorphism could significantly reduce lung cancerrisk." (PMID 26870106, 2015).
heart disease (29 papers, 2011 to 2025). "Among these transcription factors, Ikbkb, Nfkb1 and Nfkb2 have been used as drug targets for the treatment of heart disease." (PMID 35811717, 2022).
blood cancer (18 papers, 2011 to 2025). "NF-κB, a crucial transcription factor family including NFKB1, plays a significant role in hematological tumors through its regulation of cell proliferation, apoptosis, and inflammation." (PMID 41048997, 2025). "We observed that Nfkb1 exhibited higher transcriptional activity in Nrp1 + DT cells, whereas Etv6, a transcription factor known mainly for its role in hematology and blood cancers, showed higher activity in Nrp1-DT cells." (PMID 38977708, 2024).
gastrointestinal disease (11 papers, 2013 to 2026). A disease that occurs in the gastrointestinal system, excluding the hepatobiliary system. "In many experimental models of gastrointestinal diseases, deficiency of the Nfkb2 gene presents a distinct phenotype compared with phenotypes observed following deficiency of other NF-κB subunits, such as Nfkb1 or cRel." (PMID 35916405, 2022).
autosomal dominant disease (1 paper, 2019). Autosomal dominant form of disease. "NFKB1-AD comprise a group of three different autosomal dominant diseases due to mutations in the NFKB1 gene." (PMID 31736939, 2019).
NFKB1 also shares sentences with these, for which no sentence is quoted: inflammation (475 papers); liver fibrosis (468); Cerebral ischemia (372); Cognitive impairment (302); injury (265); non-small cell lung carcinoma (231); metabolic disorders (213); nasopharyngeal carcinoma (178); lung adenocarcinoma (151); Hepatitis (141); acute lung injury (135); myocardial ischemia (135); acute pancreatitis (124); kidney damage (121); head and neck squamous cell carcinoma (120); pneumonia (119); epilepsy (116); endotoxemia (114); chronic obstructive pulmonary disease (110); neurological disorders (108); pancreatitis (108); esophageal cancer (99); Crohn disease (95); esophageal squamous cell carcinoma (93); oral squamous cell carcinoma (92); diabetic retinopathy (90); HIV-1 infection (86); fibrosis (85); memory impairment (85); brain injury (81).
A further 1,331 diseases each share a sentence with NFKB1 in 81 papers or fewer.